TNF (tumor necrosis factor)
Diseases named in the same sentence as TNF in open-access papers (continued):
Sharing a sentence is not in itself a finding about the gene and the disease.
lung carcinoma (continued). "The levels of 8-isoprostane, VEGF, and TNF-α in EBC and serum of patients having primary lung carcinoma were appraised in a prior study." (PMID 41179937, 2025). "EVs also increased PD-1, CTLA-4, FOXP3, TNF-α, IL-12, and INF-γ mRNA in lung cancer patients’ immune cells." (PMID 40725070, 2025). "During the lung cancer brain metastasis, lung cancer cells secrete IL-8, MIF, and PAI-1, which activate astrocytes and induce the expression of TNF-α, IL-1β, and IL-6, thereby promoting the proliferation of cancer cells." (PMID 41268299, 2025). "In lung cancer, CD28−PD1+ and CD28−PD1− T cells displayed enhanced secretory capabilities for granzyme B, IFN-γ, and TNF-α, whereas CD28+PD1− and CD28+PD1+ T cells exhibited diminished secretory functions, consistent with our findings." (PMID 40136325, 2025). "Recognize and kill EGFRvIII-positive lung cancer cells by releasing cytokines (IFN-γ and TNF-α),and helps to inhibit the growth of transplanted tumors." (PMID 40370457, 2025). "We were unable to detect TNF-α in these samples; however, we noted a significant increase of IFN-γ in the cancerous tissue of some patients with lung cancer compared with the patient’s normal adjacent tissue." (PMID 40553564, 2025). "In our previous work, we used oral cancer, pancreatic cancer, lung cancer, and glioblastoma to demonstrate that supernatant of NK cells mediates differentiation in tumors, and we have validated this based on IFN-γ and TNF-α levels." (PMID 40890122, 2025). "To investigate the origin of type 1 inflammatory cytokines in lung cancer, we used flow cytometric analysis to evaluate the tumor bed for IFN-γ– and TNF-α–producing cells." (PMID 40553564, 2025). "Specifically, the lung cancer incidence rate in the TOFA group was 0.7 per 100 patient-years, compared to 0.5 per 100 patient-years in the TNF inhibitor group." (PMID 40282506, 2025). "Collectively, these results reveal a mechanism that suppresses TNF-induced NF-κB signaling and links OTUD4 dysfunction to inflammation-driven oncogenesis, including non–small cell lung cancer." (PMID 41062071, 2025). "Additionally, TNF-α (r = 0.400, P < 0.01), MIP-2 (r = 0.343, P < 0.01), MIP-1α (r = 0.551, P < 0.01) and MIP-1β (r = 0.403, p < 0.01) were positively associated with occurrence of lung cancer, but IFN-γ (r = −0.483, p < 0.01) was negatively associated with occurrence of lung cancer." (PMID 38813211, 2024). "In both AA and WA lung cancer patients, IL-8, IFN-γ, and TNF-α showed higher levels in plasma samples compared to the cancer-free controls." (PMID 38276239, 2024). "Our study establishes a link between the levels of IP-10, MIP-1α, MIP-1β, MIP-2, TNF-α and IFN-γ and diagnosis of lung cancer." (PMID 38813211, 2024). "Previous studies reported that niclosamide inhibits TNF-α-induced NF-κB-dependent activity, increases ROS levels in AML cells, and enhances the sensitivity of lung cancer cells to ROS12,13." (PMID 39191850, 2024). "In our previous studies, we demonstrated that pyroptosis-related cytokines TNF-α, IFN-γ, IP-10, MIP-1α, MIP-1β and MIP-2 can induce T cell infiltration into lung cancer tissues and ultimately promote the lung cancer tissue regression." (PMID 38813211, 2024). "Our previous studies indicated that pyroptosis-related cytokines TNF-α, IFN-γ, MIP-1α, MIP-1β, MIP-2 and IP-10 is important to influence the efficacy of chemotherapy drug in lung cancer tissues." (PMID 38813211, 2024). "In a previous study, LTA was found to be related to SCZ in genetic polymorphism variant, and ADAM17 was identified as an emerging therapeutic target for lung cancer and its expression was revealed SCZ through the TNF pathway." (PMID 38592583, 2024). "This is indicated by the activity of TNF, which is released when anaphylatoxins bind macrophages in various lung-related diseases like COPD and lung cancer." (PMID 39684535, 2024).
lung carcinoma (continued). "Incubation of HLMs with TSLP induced the release of TNF-α, VEGF-A, angiopoietin 2 and VEGF-C, indicating the role of TSLP system in lymphangiogenesis through a Th2-dependent pathway in lung cancer and other chronic inflammatory disorders." (PMID 38566083, 2024). "Tumor necrosis factor (TNF) is a probable crucial element in the connection between coronary artery disease (CAD) and lung cancer." (PMID 39668834, 2024). "In lung cancer, USP4 was identified as a negative regulator of TNFα-mediated lung cancer cell migration through deubiquitination of TRAF2 and TRAF6." (PMID 38802791, 2024). "In our previous studies, we found that the adaptive immunity which against lung carcinoma can be activated by pyroptotic lung cancer cells, which lead to significant increase of IFN-γ, IP-10, MIP-1α, MIP-1β, MIP-2, and TNF-α." (PMID 38813211, 2024). "Previous studies reported that niclosamide inhibits TNF-α-induced NF-κB-dependent activity, increases reactive oxygen species (ROS) levels in AML cells, and enhances the sensitivity of lung cancer cells to ROS12,13." (PMID 39191850, 2024). "Th1 cells, which release tumor necrosis factor alpha(TNF-α), IL-2, and interferon gamma (IFN-γ), contribute to antitumor immune responses in lung cancer." (PMID 36776832, 2023). "Several cytokines, such as interleukin-6 (IL-6), oncostatin M, and tumor necrosis factor-α (TNFα), induce CYP19A1 gene expression in lung cancer through the regulation of estrogen synthesis." (PMID 37047797, 2023). "Lung cancer activates macrophages via Toll-like receptor (TLR) family member TLRs and produces TNF-α, and the creation of an inflammatory environment favours the occurrence of metastasis." (PMID 37033918, 2023). "The median IL-6, TNFα, IL-1β, and IFN-γ values were higher in lung cancer cases than in the subcohort." (PMID 38067398, 2023). "The study measured the concentration of IFN-γ, TNF-α, IL-1β, IL-2, IL-4, IL-6, IL-10, and IL-12p70, in venous blood and BALF of a total of 33 patients with lung cancer and 33 patients with benign lung diseases." (PMID 37373987, 2023). "In the treatment of osteolytic metastasis, the IL-17, TNF, PI3K-Akt, TGF-beta, and lung cancer signaling pathways showed higher target enrichment results, indicating their potential." (PMID 35872837, 2022). "The KEGG pathway enrichment analysis showed that TNF, PI3K-Akt, AGE-RAGE, and IL-17 signaling pathways were the main signaling pathways of Buxue Liqi Huatan decoction in the treatment of lung cancer." (PMID 36035842, 2022). "In multiple lung cancer cell lines, EGFR signaling effectively reduced the levels of TNF-α, and the inhibition of EGFR resulted in the increased levels of TNF-α through the alteration of mRNA stability." (PMID 36204127, 2022). "This is consistent with preceding observations from our own and other groups that markedly increased levels of cytokines, including IL-2, TNFα and CXCR4, are detected in experimental and human lung cancer tissue." (PMID 36241617, 2022). "The first lung cancer-related KEGG pathway is the IL-17 signaling pathway in LUAD, while the tumor necrosis factor (TNF) signaling pathway is in LUSC." (PMID 36276869, 2022). "TNF inhibition via TNFRSF1A silencing, etanercept, or thalidomide increases sensitivity of lung cancer cells to EGFR-TKIs, whereas TNF overexpression attenuates apoptosis induction by EGFR-TKIs." (PMID 35372081, 2022). "Since several studies have reported that proinflammatory cytokines like TNFα is capable of inducing cancer cell death, it is possible that intranasal SARS-CoV-2 spike S1 can elicit the death of lung cancer cells via proinflammatory cytokines." (PMID 36428739, 2022). "The activities of SP‐1 and STAT3 induced by NF‐κB, USF1, and IL‐6 were not significantly affected by K284 treatment, but lipopolysaccharide‐ and TNF‐α‐induced SP‐1, STAT3, and AP‐1 were significantly decreased by K284 treatment in A549 lung cancer cells." (PMID 34758182, 2022).
lung carcinoma (continued). "The enrichment analysis results show that the TNF signal pathway, PI3K-Akt signal pathway, AGE-RAGE, IL-17, etc., are the main signal pathways of Buxue Liqi Huatan decoction in treating lung cancer." (PMID 36035842, 2022). "Both cytokines (IL-6, 10, 17, 27, 35; TNF-α; IFN-γ; TGF-β) and chemokines (CCL-2, 5, 18; CCR-4; CXCR-4; CX3CL-1; CXCL-1, 5, 8, 13) are very commonly targeted for lung cancer treatment, considering their biomarker roles." (PMID 34336101, 2021). "Tumor necrosis factor-α (TNF-α) enhances the adhesion of CD15, which is expressed at high levels in metastasizing lung cancer cells to the brain, and E-selectin, which is expressed on brain endothelial cells." (PMID 33466236, 2021). "LIUS-upregulated IGs were downregulated more than upregulated in proinflammatory cytokine TNF-α KO cells, IL-6 KO cells, IL-1β KO, and anti-inflammatory cytokine TGF-β-treated lung carcinoma cells." (PMID 33628851, 2021). "In lung cancer cells, Tgr5 receptor activation significantly inhibits STAT3 phosphorylation, thus TNF-α and interleukin, the inflammatory genes were decreased such as TNF-α, IL-6." (PMID 34196345, 2021). "Combined use of TNF-α and TGF-β can promote the dryness of H460 lung cancer through NF-κB and FoxM1 pathways." (PMID 35069596, 2021). "TNF-α induces the EMT in several carcinomas via transcription-factor-dependent mechanisms, supporting the interaction between TB fibrosis and lung cancer in the present study." (PMID 33567693, 2021). "Intriguingly, the activation of the TNF-α/NF-κB signaling axis has been shown to promote EMT progression and PD-L1 expression in lung cancer." (PMID 33916322, 2021). "We have previously demonstrated that TNF-α, a proinflammatory cytokine, enhances TGF-β-mediated EMT in A549 human lung cancer cells." (PMID 34789779, 2021). "TGF-β, IL-6, and TNF-α were increased in the sera and lung lysates of mice with BCG injection and subsequent lung cancer cell injection." (PMID 33567693, 2021). "TNF and VEGF are the major driving factors of CXCL-1 expression acting through PI-3K/AKT, JNK, and p38 MAPK signalling mechanisms in human lung carcinoma's epithelial cells." (PMID 34336101, 2021). "LIUS-upregulated IGs were downregulated more than upregulated in proinflammatory cytokine TNF-α KO, IL-6 KO, and anti-inflammatory cytokine TGF-β-treated lung carcinoma cells and ovarian epithelial cells." (PMID 33628851, 2021). "In another study, RAs secrete interferon-α (IFN-α) and tumor necrosis factor (TNF), which activates the STAT1 and NF-κB pathways in lung cancer cells residing in the brain." (PMID 33262947, 2020). "We have previously reported that combined treatment with TNF-α and TGF-β induces EMT of lung cancer cells." (PMID 32357159, 2020). "In fact, PD-L1 expression is induced after exposure to interferon-γ (IFN-γ) released by T effector cells, as well as after other signals such as TNF-α, VEGF, and CXCL8, ultimately promoting lung cancer progression." (PMID 32630659, 2020). "To investigate the function of MoDCs in the immune responses of lung cancer, we generated immature MoDCs by CD14+ monocytes isolated from human PBMCs and matured them using IFN-γ, R848, PGE2, and TNF-α DCs." (PMID 32655564, 2020). "The effect of TNF-α can only be realized when it binds to TNF-α receptor (TNFR1), which contains TNFR1 promoter -223/-29 in lung cancer cells." (PMID 33262947, 2020).
lung carcinoma (continued). "In lung cancer for instance, certain cytokines (IL-4, IL-5, IL-8, IL-10, IFN-γ, and TNF-α) were significantly elevated among EA compared to AA patients, whereas elevated IL-1β, IL-10, and TNF-α levels were associated with lung cancer only among AA patients." (PMID 32714862, 2020). "Another study found that enhanced cell migration by tumor necrosis factor and a similar morphology like fibroblast was found to be reduced by small CLDN-1 interfering RNA in the cells of lung cancer." (PMID 31952355, 2020). "For example, tumor necrosis factor (TNF) and vascular endothelial growth factor (VEGF) stimulated CXCL1 expression via JNK, p38 MAPK, and PI-3K/Akt signaling pathways in human lung carcinoma epithelial cells." (PMID 31998654, 2019). "Co-culture with lung cancer cell lines also increased intracellular expression of IFNγ and TNFα in DNT cells, suggesting the activation of these T cells by lung cancer cells." (PMID 30857561, 2019). "Sotetsuflavone can inhibit epithelial interstitial transformation, invasion, and metastasis of lung cancer cells in A549 cells through both PI3K/AKT and TNF-α/NF-κB pathways." (PMID 29531823, 2018). "To further explore which cells contribute to TNF-α and IL-6 production, we also detected TNF-α and IL-6 expression in AFG1-induced lung cancer cells as well as in tumor-adjacent tissues by immunohistochemical staining." (PMID 28801561, 2017). "Assessment of MMP9 by zymography assays showed that co-treatment with TNF and TGF-β cytokines markedly induced secretion of pro-MMP9 at 24 hours in breast and lung cancer cells." (PMID 28423685, 2017). "Since necrosis inhibitors, NecroX-2 and Necrostatin-1 did not alter cell death, it seemed that apoptosis is major mechanism for the suppression of cell growth in TNF-α and SAHA-treated lung cancer cells." (PMID 28099148, 2017). "Moreover, SIRT1 could contribute to the development of lung cancer through TNF-α/β-catenin axis." (PMID 28977967, 2017). "Administration of TNFR1 siRNA recovered apoptotic cell death in TNF-α and SAHA-treated lung cancer cells." (PMID 28099148, 2017). "That study detected the contents of such plasma cytokines as IL-1, IL-6, IL-10, tumor necrosis factor α (TNF-α), and TGF-β1 in 34 lung cancer patients at different time points and found the incidence of SRP as 23.5%." (PMID 29147071, 2017). "As MMP-13 is closely involved in IL-6 or TNF-α increasing tumor metastasis, we therefore focused on MMP-13 in TNF-α increasing lung cancer cell migration." (PMID 27556690, 2016). "This study demonstrates that in lung cancer at least, mast cells of both the MCT and MCTC phenotype express TNFα." (PMID 27922077, 2016). "In the present study, we demonstrated that the activation of ATM-ERK/p38-NF-κB, which induced by TNF-α in autocrine or paracrine manner, up-regulate MMP-13 expression and thereby augment lung cancer metastasis." (PMID 27556690, 2016). "In this model, ATM is the key up-steam regulator of TNF-α activated ERK/p38-NF-κB pathway, which play a vital role in promoting lung cancer cell migration by up-regulating MMP-13 expression." (PMID 27556690, 2016). "To explore the effect of TNF-α on cell migration, we firstly determined TNF-α level in a panel of lung cancer cells." (PMID 27556690, 2016). "Together, these results demonstrate that ATM-ERK/p38-NF-κB play important roles in TNF-α up-regulating MMP-13 expression and promoting lung cancer cell migration." (PMID 27556690, 2016). "In lung cancer treatment, the sensitivity of NSCLC cell lines to Smac mimetic, Compound 3/4, alone is related to autocrine-secretion of TNFα and the formation of RIP1-dependent caspase-8-activating complex." (PMID 27737687, 2016). "The inflammatory cytokines, TNF-α, IL-1 and IL-6 are elevated in COPD, CVD, and lung cancer and are potential therapeutic targets particularly in the context of acute exacerbations." (PMID 26220864, 2015).
lung carcinoma (continued). "As MMP-3/MMP-13 plays the pivotal roles in TNF-α increased metastasis, we therefore investigated the role of MMP-3/MMP-13 in IL-6 enhanced lung cancer metastasis." (PMID 26528698, 2015). "ADAM17 has been shown to shed ligands of EGFR, such as amphiregulin and TNFα, and subsequently activate EGFR, thereby improving the proliferation and migration of lung cancer cells." (PMID 25364437, 2014). "To further investigate the antagonism of the antiproliferative effects of TNF-α by RASSF1C, we assessed the activation of caspase 3/7 in breast and lung cancer cells overexpressing RASSF1A and RASSF1C that were treated with TNF-α." (PMID 24327924, 2013). "Treatment of A549 lung cancer cells with the COX-2 gene activators, PMA, IL1β and TNFα increased levels of COX-2 protein, mRNA and promoter RNA." (PMID 23999091, 2013). "Variant alleles in TNF α-308 G/A were significantly associated with higher pain severity in a study with 140 Caucasians newly diagnosed with nonsmall cell lung cancer, and this has been confirmed in another study in newly diagnosed non-Hispanic Caucasian lung cancer patients (n = 667)." (PMID 23766564, 2013). "It is possible that consistent stimulation by TNFα secreted from inflammatory cells keeps MUC1 expression in bronchial and alveolar cells at high levels to promote lung cancer development." (PMID 22457794, 2012). "To further validate the significance of NK cells’ secreted cytokines and/or rhIFN-γ and rhTNF-α in inducing differentiation in lung cancer, we treated tumors with antibodies against both IFN-γ and TNF-α to determine if we can block the NK cell- or rIFN-γ- and rTNF-α-induced differentiation of hA549." (PMID 39851518, 2025). "The enzyme-linked immunosorbent assay (ELISA) results revealed that the Tet-HER1-CAR-T cells activated by Doxy and Doxy@CaCO3-PEG in the presence of HER1-overexpressing TNBC (MDA-MB-468) and lung cancer (NCI-H23) cells effectively secreted IL-2, IFN-γ and TNF-α at comparable levels." (PMID 40927437, 2025). "TNF-α levels have been shown to increase after RT in patients with lung cancer (n=104), but its relationship with survival was not reported." (PMID 40746594, 2025). "We chose to use A549 (human lung carcinoma) cells for this analysis, as they can be efficiently infected with CHIKV, are known to be immune-competent, and respond well to exogenous (e.g., TNFα) activation of the NF-κB pathway." (PMID 40006946, 2025). "The growth of lung cancer, however, was slower when IFN-γ and TNF-α were neutralized." (PMID 40553564, 2025). "Conditioned media from MUFA-treated lung cancer cells appeared to suppress secretion of TNF-α, IL-1β, and MIP-1 cytokines from monocytes, but none reached statistical significance." (PMID 39100092, 2024). "Moreover, IL-1, IL-6, IL-8, TNF-α, and TGF-β secreted by lung cancer cells can activate downstream signaling pathways to increase VEGF expression, thereby promoting angiogenesis in the bone tumor microenvironment and indirectly facilitating bone metastasis." (PMID 38571500, 2024). "Evidence suggests that cytokines such as interleukin-1β (IL-1β), IL-6, interleukin-7 (IL-7), interleukin-8 (IL-8), interleukin-11 (IL-11), tumor necrosis factor-alpha (TNF-α), TGF-β, and C-C motif chemokine ligand 12 (CCL12) play significant roles in the bone metastasis of lung cancer." (PMID 38571500, 2024). "Similarly, CircTMEM30A was highly expressed in COPD patients with lung cancer, and it regulated the expression of TNFα through miR-130a, thereby promoting the progression of COPD and lung cancer." (PMID 38601461, 2024). "Furthermore, studies have shown that tumor necrosis factor (TNF) and vascular endothelial growth factor (VEGF) can stimulate the expression of CXCL1 in human lung carcinoma epithelial cells 29-31." (PMID 39132161, 2024).